INS (insulin)
Diseases named in the same sentence as INS in open-access papers (continued):
Sharing a sentence is not in itself a finding about the gene and the disease.
diabetes (continued). "The treatment and management of diabetes mellitus (DM) with conventional therapies, such as insulin injections and oral hypoglycemic agents, present significant challenges due to their side effects and burdensome administration." (PMID 38931040, 2024). "HTA can be applied to both treatments for NCDs, such as insulin analogues for the management of diabetes, and also to interventions that seek to reduce disease prevalence and incidence in the first place." (PMID 38470940, 2024). "With a steadily increasing number of people living with diabetes requiring insulin, strategies must urgently be developed to reduce insulin prices and ensure affordable and reliable access in all parts of the world." (PMID 38536176, 2024). "Type 1 diabetes mellitus (T1DM) is a chronic autoimmune condition characterized by the destruction of insulin-producing pancreatic beta cells." (PMID 38882982, 2024). "Mustard has been reported to control blood sugar levels in people with diabetes by enhancing insulin secretion, improving the utilization of glucose, and reducing glucose absorption from the gut." (PMID 39519546, 2024). "According to the Japanese blood donation standards, blood donations from people taking diabetes medications, including insulin, oral hypoglycemic drugs, antibody drugs, and immunosuppressive drugs, are not allowed." (PMID 39247010, 2024). "The index child developed diabetes at the age of 5 years, the individual currently in adult age requires multiple daily insulin injections and already had complications onset." (PMID 38509065, 2024). "In order to elucidate the effect of Reducose® in anti-diabetic effects, blood glucose levels, insulin levels, and liver and lipid concentrations were investigated in a Sprague-Dawley rat model of high-fat diet/streptozotocin-induced diabetes." (PMID 38333854, 2024). "In another study including 2090 individuals in remission 2 years after gastric bypass surgery, the 20% who relapsed at 9 years were more likely to have been on insulin, have had an elevated HbA1c and have had diabetes of longer duration prior to intervention." (PMID 38189935, 2024). "A meta-analysis demonstrated that adopting healthy eating habits can improve insulin sensitivity, thereby reducing diabetes-related complications." (PMID 39064637, 2024). "These innovative system aims to bridge the gap between traditional insulin pumps and CGMs, providing a more seamless and dynamic approach to diabetes care." (PMID 38659016, 2024). "Although female mice are often excluded from diabetes research being less glucose intolerant and less insulin-resistant than males, we studied a 1-year-old female cohort." (PMID 38396259, 2024). "Diabetes mellitus (DM) is a heterogeneous disorder of metabolism characterized by chronic high blood glucose levels resulting from either deficiency in insulin secretion or insensitivity of tissues to insulin or both." (PMID 38594659, 2024). "This double-blind, randomized study involved 468 subjects with HbA1c levels ranging from 7.0% to 10.5% and stage 3 CKD who were receiving standard diabetes therapy, such as metformin, insulin, and/or sulfonylureas." (PMID 39000033, 2024). "An increase in the frequency of diabetes was also observed in iron overload diseases (hemochromatosis and β - thalassemia) due to insulin resistance and destruction of pancreatic β cells." (PMID 39839287, 2024). "The study revealed that SCL can be used successfully for diagnosing diabetes and monitoring the status involving insulin intervention." (PMID 38565532, 2024). "A common metabolic disorder, diabetes mellitus occurs when there is insufficient supply of insulin (Type I) or when the body is resistant to insulin (Type II)." (PMID 38658923, 2024). "Glucotoxicity is a condition that leads to β-cell death, driving a decrease in insulin secretion and leading to hyperglycemia and, eventually, diabetes." (PMID 39056663, 2024).
diabetes (continued). "Diabetes is a chronic metabolic disorder characterised by high blood sugar levels due to impaired insulin production or insulin resistance." (PMID 38881209, 2024). "Maturity-onset diabetes of the young (MODY) is the most common type of monogenic diabetes, accounting for ~ 2–5% of individuals with diabetes and characterised by an early onset, autosomal dominant inheritance, and insulin independence." (PMID 37812285, 2024). "Diabetes management (e.g., missed and mistimed insulin dosing, mismatched food intake, and correction dose delivery) and glycemic outcomes were assessed." (PMID 37855818, 2024). "Conversely, the duration of diabetes at the time of prescribing basal insulin decreased progressively (from 11.4 ± 8.4 to 8.8 ± 7.8 and to 7.7 ± 7.2 years), suggesting a timely and more accurate prescribing attitude of Italian diabetologists." (PMID 38441838, 2024). "Summarizing, miR-16-5p is known to be the most important microRNA involved in insulin resistance pathway in many tissues during diabetes confirming the diabetic states." (PMID 38191820, 2024). "Diabetes mellitus is a metabolic disorder in which pancreatic beta cells don’t produce enough insulin that can lower hyperglycemia in the blood." (PMID 38565861, 2024). "Diabetes is a chronic condition characterized by the inability of the pancreas to produce adequate amounts of insulin or the body’s inefficiency to properly use the available insulin." (PMID 39460030, 2024). "In conclusion, the comprehensive exploration of diabetes management presented in this report underscores the dynamic evolution of insulin delivery systems." (PMID 39065641, 2024). "From the sub-analysis, there was better insulin adherence observed among patients who received the USM-IAM in patients with diabetes for more than 10 years, compared to shorter diabetes duration." (PMID 39020348, 2024). "Diabetes mellitus (DM) refers to a spectrum of metabolic disorders arising from insufficient insulin secretion, diminished insulin sensitivity, or a combination of both, leading to elevated blood sugar levels." (PMID 39449925, 2024). "Damage to pancreatic β-cell induced by oxidative stress or glucotoxicity lowers Pdx-1 expression, subsequently inhibits insulin production, and promotes diabetes development." (PMID 38234664, 2024). "Do you know how to use insulin pumps and continuous glucose monitoring systems in diabetes mellitus management?" (PMID 39188797, 2024). "For individuals with diabetes, particularly those with type 1 diabetes or advanced type 2 diabetes, insulin therapy plays a central role in regulating blood glucose levels." (PMID 38542928, 2024). "The generation of insulin-producing cells to compensate for their absolute or relative shortage in type 1 (T1D) and type 2 (T2D) diabetes is an appropriate therapeutic strategy." (PMID 38702347, 2024). "Cigarette smokers with diabetes pose a significant public health concern since they face more challenges in insulin dosing and glucose control." (PMID 38791732, 2024). "Fully automated insulin delivery (i.e., an artificialpancreas)would revolutionize diabetes disease management, minimize negativesecondary disease outcomes, and simultaneously reduce health carecosts and system burdens." (PMID 39584534, 2024). "In diabetes, ferroptosis exacerbates ER stress, impaired insulin biosynthesis, and β-cell death by inhibiting the expression of oxidoreductases such as glutathione peroxidase (GPX4), and the interplay of iron–sulfur (Fe-S) clusters." (PMID 38890991, 2024). "There are many conventional anti-diabetics, including oral drugs and exogenous insulin bolus, in addition to diet and exercise, that can temporarily reduce hyperglycemia or promote insulin sensitivity in target tissues." (PMID 39468609, 2024).
diabetes (continued). "Diabetes is a chronic disease in which the pancreas is unable to produce insulin or the human body is unable to use the insulin produced effectively, resulting in an imbalance in glucose metabolism or an increase in blood sugar levels." (PMID 38371502, 2024). "Diabetes is a metabolic disorder of multiple etiological factors that occurs mainly due to impaired secretion of insulin by damaged pancreatic beta cells or impaired insulin activity leading to failure in the metabolism of carbohydrates, proteins, and lipids." (PMID 39014510, 2024). "A literature review revealed that adherence to insulin is generally poor among people with diabetes, and the adherence rates are lower than those for oral hypoglycaemic agents." (PMID 39020348, 2024). "Literature indicates that the likelihood of hypoglycemia is elevated in patients who have been using insulin for an extended period and have had a prolonged history of diabetes." (PMID 39583394, 2024). "Nevertheless, advanced diabetes treatments, such as those incorporating mHealth and insulin pumps, consistently appear to improve PS, treatment-related knowledge, adherence, and QoL." (PMID 39765957, 2024). "The choice to exclude was made because the most frequently reported diabetes medications in the sample act to acutely lower blood glucose levels either directly or through influencing insulin secretion." (PMID 38829901, 2024). "Diabetes is characterized by hyperglycemia, resulting from insulin resistance (IR) and impaired insulin secretion by pancreatic beta cells." (PMID 39834366, 2024). "Diabetes mellitus is a multifactorial condition characterized by insulin resistance (IR) and insufficient insulin secretion from pancreatic β-cells in response to glucose." (PMID 39436903, 2024). "GL Pharmaceuticals is a leading pharmaceutical company in the diabetes industry with about 20 years of experience in manufacturing and marketing insulin glargine U100 (branded as Basalin®)." (PMID 39170740, 2024). "Traditional treatments for diabetes include insulin injections and oral medications, but these can have side effects and are not always effective." (PMID 38667785, 2024). "Westerners and East Asians including the Japanese have increased insulin resistance and decreased insulin secretion as they progress from normal glucose tolerance to impaired glucose tolerance and diabetes." (PMID 40607157, 2024). "Overall, the prevalence, diabetes medication usage, and insulin usage were 26.3%, 12.1%, and 2.0%, respectively." (PMID 39356700, 2024). "For example, insulin, a medication to manage diabetes, can be injected, as can crystal methamphetamine, an illicit stimulant." (PMID 38760681, 2024). "The landscape of diabetes management has come a long way, thanks to the continuous evolution of insulin preparations and analogs." (PMID 39734941, 2024). "The Metformin in Gestational Diabetes (MiG) study demonstrated higher acceptability for metformin over insulin, despite metformin's gastrointestinal side effects." (PMID 38855483, 2024). "Dopamine agonists alleviate hyperglycemia in patients with diabetes, whereas their antagonists induce higher glucose and insulin secretion." (PMID 38517904, 2024). "Trigonelline is beneficial in the prevention and treatment of diabetes and diabetic complications by inhibiting intestinal glucose uptake, promoting β cell regeneration and insulin secretion." (PMID 39902076, 2024). "Mitochondrial dysfunction is synonymous with β-cell dysfunction in diabetes, it impairs insulin secretion and sensitizes β-cells to an environment high in metabolic/nutrient stress and cell death." (PMID 38404962, 2024). "The mechanisms by which, diabetes increases risks of hypertension can be explained through disturbed sodium homeostasis, insulin resistance, enhanced volume expansion and prominent resistance within peripheral vessels." (PMID 38218755, 2024).
diabetes (continued). "Glycosylated haemoglobin (HbA1c) was 11.6% (103 mmol/mol), prompting initiation of multiple daily insulin injections and diabetes education." (PMID 39845887, 2024). "Patient 2, the younger brother, was born via spontaneous delivery at term after a pregnancy complicated by maternal diabetes requiring insulin therapy." (PMID 39723426, 2024). "In diabetes, when blood glucose levels are elevated, insulin and stress hormones are also elevated, creating an inflammatory environment." (PMID 38201008, 2024). "In the IET group, 32.8% showed further deterioration of their diabetes mellitus levels (necessity for oral antidiabetic medication or insulin; p = 0.012)." (PMID 38347181, 2024). "Pharmacological therapies for treating diabetes include oral agents, non-insulin injectable agents and insulin." (PMID 39684653, 2024). "Secondly, we were unable to assess the effect of exogenous insulin as all donors in this study with type 1 diabetes (> 90% of our donors with diabetes) were receiving insulin treatment." (PMID 38214784, 2024). "Uric acid affects the occurrence and development of diabetes and its complications through pathological mechanisms such as inflammation, oxidative stress, vascular endothelial injury, and inhibition of insulin signaling pathways." (PMID 38725871, 2024). "We investigated how weight reduction, caused by bariatric surgery, influences two main pathogenetic mechanisms of diabetes development—insulin resistance and hormonal impairment." (PMID 39598143, 2024). "In contrast to this under fed conditions, AGE supplementation demonstrated a notable improvement in pancreatic beta cell insulin levels compared to the untreated diabetes group, with a statistically significant increase observed (p < 0.01)." (PMID 38778421, 2024). "These pathways are essential for controlling energy homeostasis and are related to insulin sensitivity, glucose tolerance, hepatic steatosis, obesity, and diabetes." (PMID 38399444, 2024). "Subjects received diabetes education and glucose monitoring training, with insulin titration overseen by a diabetes nurse." (PMID 39765957, 2024). "A diagnosis of secondary decompensated diabetes was then made, and the patient started basal-bolus insulin therapy." (PMID 38294658, 2024). "The development of devices for continuous subcutaneous insulin infusion (CSII or insulin pumps) dramatically improved medical care for patients with diabetes mellitus." (PMID 39509638, 2024). "For this dataset, specific features such as Glucose, Blood Pressure, Skin Thickness, Insulin, BMI, and Diabetes Pedigree Function containing values of 0 were replaced with their respective median values." (PMID 38718024, 2024). "Most importantly, xylose also has hypoglycemic properties that help promote insulin secretion in the body, reduce blood glucose levels and control the onset or progression of metabolic diseases such as diabetes." (PMID 39257903, 2024). "In total, 45 patients had diabetes, with 55.6% (25 patients) needing insulin therapy for diabetes control in the previous three months." (PMID 39144846, 2024). "Insulin is a mainstay of diabetes care, contributing to a treatment goal of near‐normal blood glucose levels to prevent diabetes‐related complications." (PMID 36992575, 2024). "Mediation analyses examined the role of oxidative stress markers, inflammatory markers, metabolic syndrome, body composition, diabetes, and insulin." (PMID 38903577, 2024). "The results of the study demonstrated that short-term oral treatment with ALA significantly increases peripheral insulin sensitivity in patients with type 2 diabetes mellitus, bringing it to a level almost similar to that of subjects in the control group." (PMID 39456481, 2024). "FBG is an indicator used to diagnose and monitor diabetes, reflecting the basal insulin secretion function of pancreatic β-cells." (PMID 39301316, 2024).
diabetes (continued). "This hormone influences some of the insulin target organs such as adipocytes, skeletal muscle cells, and the liver, and is a potential link between obesity and type 2 diabetes mellitus." (PMID 39065709, 2024). "Type 2 diabetes mellitus (T2DM) is a prevalent metabolic syndrome characterized by chronic hyperglycemia after either inadequate insulin production, insulin resistance, or both." (PMID 39479098, 2024). "The liver is one of the main targets of insulin and controls metabolic profiles; hence, its function plays an important role in the development of metabolic disorders such as obesity and diabetes." (PMID 39570868, 2024). "In this form of diabetes, the immune system mistakenly targets and destroys the insulin‐producing beta cells in the pancreas." (PMID 39135385, 2024). "Insulin pumps and CGMs have brought forth a revolution in diabetes care, providing patients with unprecedented real-time insights into glucose levels and precise control over insulin administration." (PMID 38666804, 2024). "Previous studies have shown that UC-MSCs can stimulate the proliferation and regeneration of islet β-cells, improve insulin secretion and control blood glucose levels in diabetes." (PMID 39000700, 2024). "High glucose-induced generation of OS is known to lead to resistance to insulin and impaired β-cell function, contributing to the pathogenesis and progression of diabetes mellitus." (PMID 39199149, 2024). "These systems combine CGM and insulin pump technologies with advanced algorithms to automate insulin delivery, reducing the burden of diabetes management." (PMID 39310514, 2024). "Previous studies have demonstrated that medications commonly utilized for managing MetS or diabetes, including intranasal insulin, metformin, incretin-based therapies, and thiazolidinediones, can also ameliorate some dementia symptoms." (PMID 38934020, 2024). "Trends in insulin prescriptions in diabetes indicate a relevant increase in the number of insulin users among T2D patients, with around 17.4% and 52% of them, respectively, on basal-only and basal-bolus regimens." (PMID 39200316, 2024). "Stem cell therapy is an effective way to cure diabetes and other pancreatic‐related diseases, which can be achieved by different methods of inducing insulin‐producing cells." (PMID 38599852, 2024). "In some cases, weight loss is enough to restore BG to a normal level, which eliminates diabetes or even lowers the need for insulin therapy or other medications to control diabetes." (PMID 38564266, 2024). "Insulin signaling mechanisms are complex, yet in terms of its role in diabetes, the focus will be on its role in glucose metabolism in target tissues such as the liver, adipose tissue, and skeletal muscles." (PMID 39199336, 2024). "Nurses should be trained to have adequate knowledge about diabetes and insulin to ensure sufficient consultation skills." (PMID 39074147, 2024). "Only after the publication of the DCCT trial in the 1990s (showing that intensive insulin treatment prevented diabetes-related complications) did continuous subcutaneous insulin infusion (CSII) device use start to increase in clinical practice." (PMID 39099754, 2024). "Pediatric patients with new-onset diabetes mellitus (NODM) or established diabetes mellitus (DM) requiring insulin initiation have traditionally required inpatient admission for ≥1 day for management and education." (PMID 39568636, 2024). "Relevant kidney biopsies were identified from 17 children known to have type 1 diabetes mellitus, defined as requirement for treatment with insulin." (PMID 38123711, 2024). "STZ’s mechanism involves the partial destruction of β-cells, which are responsible for producing insulin, thereby inducing diabetes in experimental animals." (PMID 38929670, 2024). "In type 1 diabetes mellitus, less insulin is generated, whereas in type 2, the body has problems utilizing the insulin that is produced." (PMID 38577302, 2024).